ESR1 (estrogen receptor 1)
Diseases named in the same sentence as ESR1 in open-access papers (continued):
Sharing a sentence is not in itself a finding about the gene and the disease.
breast cancer (continued). "The region of this locus does not overlap with the position of the ESR1 gene at 6q25.1-q25.2 or with the more recently suggested breast cancer susceptibility locus on 6q14.1, and it has not been reported in other studies as a BC risk locus." (PMID 38397208, 2024). "The role of FOXA1 in basal breast cancer is determined by ESR1 expression." (PMID 38605023, 2024). "Rad1901 has recently been approved for treatment of advanced ESR1 mutant breast cancers." (PMID 38978585, 2024). "Evaluation of ESR1 fusion functionality in various cellular contexts begins to offer an understanding in how a 3′ fusion partner may affect the function of one of breast cancer's most prognostic and clinically actionable genes, ESR1." (PMID 39207954, 2024). "In addition, the AMPA-associated hypomethylation at the ESR1 promoter is interesting, given the potential link between AMPA and breast cancer risk and the potential for glyphosate/AMPA-induced endocrine disruption, reviewed in this paper." (PMID 39200696, 2024). "There was a non-significant difference in the correlation between IFRD1 and ESR1 gene expression levels in breast cancer patients; additionally, those patients had significantly negative ER statuses, corroborating the lack of a relation between its action and the hormonal status of the patient." (PMID 39765744, 2024). "Mutations in ESR1 are not usually detected in primary breast cancers; rather, they are found in estrogen-positive breast cancer patients who have been previously treated with aromatase inhibitor therapy." (PMID 38791037, 2024). "For example, in CD4+ T-cells, BCL9 for B-cell acute lymphoblastic leukemia (B-ALL); GAS7 and PRDM16 for Acute myelogenous leukemia (AML); ESR1 for breast cancer; and GRIN2A for colorectal, lung, and gastric carcinoma were differentially methylated between PWH and PWoH." (PMID 38466776, 2024). "Importantly, ESR1 expression is higher in breast cancer tissues than in other malignant and healthy tissues, including healthy breast tissues." (PMID 38335301, 2024). "The need to identify robust markers to predict the response to endocrine therapy in ESR1-related tumors, such as breast cancer, has received increasing attention, because only 50–70% of patients with receptor-positive tumors (identified by high ESR1 expression) respond to this treatment." (PMID 38279245, 2024). "This pattern is exemplified by the selection for activating mutations in ESR1, which do not appear to play a role in the development of primary breast cancer, but rather in acquired resistance to anti-estrogen therapies." (PMID 38321573, 2024). "We previously reported that TWIST1 induces the transcriptional activation of mesenchymal genes such as VIM (Vimentin) and SNAI2 (Snail 2) but induces the transcriptional repression of epithelial genes such as CDH1 (E-cadherin) and ESR1 (ERα) in breast cancer cells." (PMID 38893094, 2024). "Notably, PIK3R1, AKR1C3, and EGFR mRNAs were significantly downregulated in breast cancer tissue, while ESR1 was significantly upregulated." (PMID 39204124, 2024). "We recognize that a subset of the genes we identified in our analysis of this dataset are opposite of what has been reported in prior work, specifically MMP9 and ESR1, as being upregulated in Letrozole-resistant breast cancer tumors, which agrees with our findings." (PMID 39057065, 2024). "Among them, many regulatory associations have been revealed; for instance, miR-22 was demonstrated to inhibit ESR1 expression in breast cancer, whereas H19 could act as a sponge of miR-22 in many cell types (Gan, Lv & Liao, 2019; Sun, Mao & Ji, 2021)." (PMID 38549776, 2024). "Interestingly, when LINC00052 expression is inhibited, ‘Pro-oncogenic action of estradiol_estrogen receptors’ as well as ‘ESR1/ESR2 ratio in breast cancer’ signalling pathways are modulated." (PMID 38832821, 2024).
breast cancer (continued). "In breast cancer cell lines, palazestrant inhibits estrogen-induced transcriptional activity and blocks agonist activity on estrogen-induced genes, as well as antiproliferative activity in WT and ESR1 mutant cells." (PMID 39767607, 2024). "Nowadays breast cancer clinical treatment selection is based on the immunohistochemical (IHC) determination of four protein biomarkers: Estrogen Receptor 1 (ESR1), Progesterone Receptor (PGR), Human Epidermal Growth Factor Receptor 2 (HER2), and proliferation marker Ki-67." (PMID 39000458, 2024). "However, fulvestrant’s efficacy against ESR1 mutant metastatic breast cancer in the second line is modest, with median PFS ranging from 3 to 4 months." (PMID 38339371, 2024). "Notably, the presence of ESR1-positive follicular dendritic cells in lymph nodes has been recognized as a novel prognostic marker for breast cancer, aiding in therapeutic decision-making." (PMID 39684286, 2024). "It has demonstrated strong efficacy in wild-type and ESR1-mutant breast cancer xenograft models." (PMID 38800404, 2024). "Many pathogenic gene mutations common to breast cancer, such as Pten, Brca2, Atm, Cdh1, Chek2, Nf1, Arid1a, Pik3ca, and Esr1, revealed no alterations between NT2.5 and NT2.5-LM." (PMID 38717519, 2024). "Additionally, ESR1 demonstrated significant alterations in breast cancer stages, while EGFR showed significant changes in colon cancer stages." (PMID 39204124, 2024). "In Hormone-Receptor-positive (HR+) breast cancer, representing approximately 70% of cases, acquired resistance can be monitored using LB targeted to mutations occurring within the Ligand-Binding Domain (LBD) of the Estrogen Receptor-1 (ESR1) gene." (PMID 39201516, 2024). "Current data identifies mutations in the ER of primary breast tumors, but also indicates that the acquisition of ESR1 mutations can occur in metastatic breast cancer cells, independent of their presence in the primary tumor." (PMID 38567308, 2024). "Furthermore, the higher co-expression of Esr1, Esrra and Spp1 mRNA in human breast cancers emphasizes the importance of ERRα in conjunction with ERα in driving SPP1 expression and, potentially, breast cancer progression." (PMID 39682141, 2024). "ASH2L upregulates GATA3‐induced transcription of ESR1 in breast cancer cells." (PMID 37974198, 2023). "There is evidence that ESR1 gene fusions in estrogen receptor-positive breast cancer promote endocrine therapy resistance and metastasis, thus ESR1 gene fusions may have a role in ovarian cancer progression." (PMID 37400526, 2023). "In breast cancer, estrogen receptor 1 (ESR1) regulates the TFF1 expression." (PMID 37037466, 2023). "Notably, all four patients who died during the study period had initially high levels of ESR1 expression, suggesting a potential link between ESR1 overexpression and reduced survival in breast cancer patients." (PMID 38114755, 2023). "After estrogen binding, ESR1 translocates to the nucleus and binds to estrogen receptor elements in enhancer regions of the genome, mediating gene transcription during normal physiological processes, but also in the course of breast cancer tumorigenesis." (PMID 36980614, 2023). "Moreover, an analysis of hotspot mutations in the genes PIK3CA, ESR1, AKT1 and ERBB2 frequently present in breast cancer was performed." (PMID 36823365, 2023). "However, to the best of the authors’ knowledge, no study has previously investigated the expression of miRNAs and ESR1 target mRNA in canine mammary tumors." (PMID 36978627, 2023). "Indeed, expression of PDGFC was inversely correlated with ESR1 expression in breast cancer cell lines, and Pdgfc expression was significantly lower in cultured ER+ TSAE1 and HRM1 tumor cells than in ER− D2A1 and 4T1 cells." (PMID 36914817, 2023).
breast cancer (continued). "Finally, the progesterone-induced downregulation of PR, a target of ESR1, further supports the hormonal interplay between progesterone and estrogen signaling pathways in breast cancer." (PMID 37395734, 2023). "Whole-exome and transcriptome analyses of patients with ER-positive metastatic breast cancer identified mutations in ESR1, affecting its ligand-binding domain (LBD), suggesting that activating mutations in ESR1 is a key mechanism in acquired endocrine resistance in breast cancer therapy." (PMID 36831644, 2023). "Estrogen receptor α (ERα), encoded by the ESR1 gene, is a key prognostic and predictive biomarker firmly established in routine diagnostics and as a therapeutic target of breast cancer, and it has a central function in breast cancer biology." (PMID 36831182, 2023). "In this study, we used real-world clinical data and gene expression datasets (ERBB2, ESR1, PGR) to provide examples of how g3mclass may help overcome the problems of over-/underdiagnosis and equivocal results in diagnostic tests for breast cancer." (PMID 36335194, 2022). "ESR1 amplification may be a common mechanism in proliferative breast disease and a very early genetic alteration in a large subset of breast cancers." (PMID 35563727, 2022). "For example, breast cancer cells specifically express TF ESR1, together with its cooperating TF GATA3, inducing global transcriptional network changes by mediating enhancer accessibility as well as eRNA expression in breast cancer cells to promote tumorigenesis." (PMID 36232885, 2022). "By identifying gene expression levels that are common between ESR1 knockdown breast cancer cells and AD-related neuroinflammation, it may be possible to speculate on the molecular mechanisms underlying the increased risk of AD in postmenopausal women." (PMID 36326669, 2022). "The basal breast cancer subtype is characterized by triple negativity (for ESR1, PgR and HER‐2), expression of EGFR and cytokeratin 5/6 and is a more aggressive subtype; associated with high tumour grade, younger age and poor prognosis, including shorter disease‐free and overall survival." (PMID 35579852, 2022). "Indeed, mutant ESR1 was detected in the circulating tumor DNA (ctDNA) of approximately 14% of HR+ breast cancer patients during disease progression." (PMID 36045910, 2022). "In addition, a role of ERα-LBD in breast cancer stemness and malignancy was suggested by RNA-seq analysis and qPCR demonstrating an enrichment of the ESR1-LBD transcript in fulvestrant resistant CD44High tumor cells." (PMID 35999225, 2022). "ESR1 fusions were identified in more aggressive forms of breast cancer (ET resistant MBC and Luminal B breast cancer) and can guide the diagnosis and the development of therapeutic strategies to treat a subset of patients with tumors that harbor these ESR1 alterations." (PMID 36686845, 2022). "Among these, CXCL12, ESR1, IGF1, and FOS were associated with breast cancer survival." (PMID 35463082, 2022). "This was further corroborated by PAM50-based analysis, where we found MCF7 ESR1 mutant cells were predominantly called as basal subtype with above 70% probability and exhibited gene expressional similarities to basal breast cancer cell lines." (PMID 35440136, 2022). "Thus, BET inhibition has the potential to both prevent and overcome ESR1 mutant–induced endocrine therapy resistance in breast cancer." (PMID 35881485, 2022). "Accordingly, breast cancers are classified as tumors expressing estrogen receptor-α (ERα/ESR1), progesterone receptor (PGR) and/or epidermal growth factor (EGF) family receptor HER2/ERBB2, which emanate from luminal epithelial progenitors and are classified as luminal-A or -B." (PMID 36171192, 2022).
breast cancer (continued). "Methods were tested on breast cancer RNA-seq data and compared with regards to the number of genes identified at various bimodality index (BI) thresholds and ranking of known bimodally expressed genes (ESR1, HER2, and PGR)." (PMID 35639779, 2022). "Although several spliced isoforms for breast cancer genes such as ESR1 and ERBB2 have been previously identified, current annotations widely used for transcriptome analysis, such as RefSeq and GENCODE, do not contain the level of complexity revealed by our LR-seq analysis." (PMID 35044822, 2022). "Mutations in ESR1 can cause activation of ER independent of estrogen levels, allowing for the upregulation of breast cancer cell proliferation in an endocrine therapy-resistant mechanism." (PMID 35505937, 2022). "EZH2 has been reported as a transcriptional activator of ESR1 expression in breast cancer cells." (PMID 35326450, 2022). "Thus, our findings show that BET inhibitors, as a class, inhibit ESR1 Y537S–driven breast cancer growth in in vitro, ex vivo, and in vivo models." (PMID 35881485, 2022). "Additionally, DSCAM-AS1 sponges the activity of miR-130a that regulates the expression of ESR1 by binding to its 3’-UTR to mediate the effect of progesterone in breast cancer cells." (PMID 36578092, 2022). "One example of bimodal gene expression is the estrogen receptor (ESR1) in breast cancer." (PMID 35639779, 2022). "Additionally, we also found that expression of YAP (YAP1) was negatively correlated with ERα (ESR1) in ER+ breast cancer patients, but the ESR1 level was still positively correlated with YAP‐ and obesity‐associated signatures." (PMID 35182054, 2022). "According to previous studies, colorectal patients with MLL3 mutation could benefit from ICI therapy, while MST1R signaling promoted therapeutic resistance in ESR1 mutant breast cancer." (PMID 35997004, 2022). "For example, the activation of ESR1 can globally increase eRNA transcription in breast cancer." (PMID 35864475, 2022). "In recent years, ESR1 therapy garners more attention in the effective treatment of breast cancer." (PMID 35359459, 2022). "For example, methylation by SETD7 improves the stability of ERα (ESR1) in breast cancer (BC), which may be of relevance to endocrine resistance." (PMID 36551516, 2022). "The PIAS1 epigenetic pathway is increased in breast cancer and, in addition to silencing genes such as ESR1, also silences the tumor suppressor WNT5A, which has been shown to increase self-renewal of breast tumor initiating cells and requires PIAS1 activity as a SUMO E3 ligase." (PMID 35887358, 2022). "Studies of hormone-regulated cancers, such as breast cancer and prostate cancer, have shown that pathogenic dysregulations of gene expression are mediated through risk variants altering binding affinities of master TFs, such as FOXA1, ESR1, and AR." (PMID 36402776, 2022). "Activating ESR1 mutations are acquired mutations and not a clonal selection, as they are not detected in primary breast cancer and they are found in the subclonal population." (PMID 35053474, 2022). "Interestingly, miR-130a also showed a significant inverse correlation to DSCAM-AS1 and ESR1 expression in 752 TCGA breast cancer samples." (PMID 36578092, 2022). "Primary tumors in which ESR1 was unmethylated never displayed ER expression loss in metastases, implicating ESR1 DNA methylation as a potential driver of breast cancer metastasis." (PMID 36140723, 2022). "More recently, breast cancer PDX models that preserve patient intratumoral heterogeneity and clonal architecture have been reported, including endocrine therapy-resistant models that feature ERα Y537 mutations, ESR1 gene amplification, or ESR1/YAP1 fusion." (PMID 36045910, 2022).
breast cancer (continued). "In addition, MSI2 directly regulates estrogen receptor 1 (ESR1) expression, which is a well-known therapeutic target, by binding to the specific sites in ESR1 RNA and increasing the stability of ESR1 protein, thus affecting the growth of breast cancer cells." (PMID 36059653, 2022). "Hence, our work highlights the utility of a set of isogenic breast cancer cell lines for investigating new strategies for the treatment and diagnosis of ESR1 mutant breast cancer." (PMID 36198774, 2022). "Knocking down ESR1 expression may enhance the efficacy of radiation-induced ferroptosis via the NEDD4L/CD71 pathway in breast cancer." (PMID 36467032, 2022). "To test this hypothesis, we examined known bimodal genes that were relevant to disease progression in breast cancer, including ESR1, HER2, and progesterone receptor (PGR)." (PMID 35639779, 2022). "mRNA levels were low for ESR1 compared to breast cancer cell line MCF7 in the HL cell lines." (PMID 36430230, 2022). "As laso and RAD1901 are under clinical evaluation in Y537S ESR1 breast cancer patients, we measured the anti-proliferative activities of T6I-29-1A alongside 4OHT, ICI, laso, and RAD1901 at 1 μM in homozygous Y537S ESR1 MCF7 cells (kindly donated by Dr. Sarat Chandarlapaty)." (PMID 36517522, 2022). "ESR1 plays an important role in the occurrence and development of breast cancer." (PMID 35686089, 2022). "In conclusion, the present results suggest that PSPC1 would facilitates hormone-dependent breast cancer proliferation by exhibiting RNA processing of ESR1 and SCFD2, the latter further contributes to anti-apoptotic or proliferative responses by modulating the expression of DDIAS and MYBL1." (PMID 35681031, 2022). "Even though the incidence of ESR1 mutation is low in HR + breast cancer not previously exposed to endocrine therapy, it rapidly increases once the HR + tumor is under the selection of antiestrogen therapy." (PMID 36229710, 2022). "ESR1-MUT breast cancer is likely still somewhat sensitive to tamoxifen and fulvestrant, although novel SERMs, SERCAs, and SERDs may improve efficacy further." (PMID 34392831, 2021). "In a Europe-wide external quality assessment, we compared performance of an mRNA-based method [Xpert® Breast Cancer STRAT4 (CE-IVD)] for determining ESR1, PGR, ERBB2, and MKI67 expression against the gold standard [immunohistochemistry (IHC)/HER2 in situ hybridization (ISH)]." (PMID 34572945, 2021). "For example, “prolactin/ERK (extracellular signal-regulated kinase) signaling in breast cancer” was ranked ninth among GPSM1 statistically significant pathway analysis, and “mitogenic action of ESR1 (Estrogen Receptor 1) (membrane) in breast cancer” was ranked 15th for GPSM4." (PMID 34572330, 2021). "SALL1, SALL2, and ESR1 expression analyses could help to categorize breast cancer patients who may benefit from combined therapies: tamoxifen and DNMTi." (PMID 34944911, 2021). "The ESR1 mRNA is differentially expressed in breast cancer subtypes." (PMID 34831189, 2021). "Additionally, we identified a significant association of genes involved in treatment response in breast cancer with genes producing splicing-derived neoepitopes (ERBB2, ESR1, TIMP1, ABCC3) or potentially depleted self-epitopes (AKT1, CCNE1, RET, TFF3)." (PMID 34529669, 2021). "This time, CausalPath results were not significant in terms of the overall network size (p = 0.2218); nevertheless, they indicate that ESR1 is significantly more active in luminal breast cancers, suggested by both its protein levels and the changes in its downstream." (PMID 34179843, 2021). "Importantly, genes related to breast cancer, such as ESR1 or PALB2 were observed in all the analyzed samples, before and after culture." (PMID 34071445, 2021).